ENSG00000280148 (novel transcript)
Gene: Protein-coding gene on chromosome 6 (143,857,318 to 143,938,471, forward strand). Ensembl gene ENSG00000280148.
Genetic constraint (gnomAD): Missense variants: 157 observed, 173.89 expected, observed/expected ratio (o/e) 0.9, 90% interval 0.79 to 1.03. Synonymous variants: 37 observed, 61.58 expected, observed/expected ratio (o/e) 0.6, 90% interval 0.46 to 0.79.